BCAS1 (brain enriched myelin associated protein 1)
Description:
Required for myelination.
Synonyms: AIBC1; NABC1; PMES-2
Tractability: PROTAC: its protein half-life has been measured.
Gene: Protein-coding gene on chromosome 20 (53,936,777 to 54,070,641, reverse strand). Ensembl gene ENSG00000064787.
Subcellular location: Cytoplasm
Subcellular location (Human Protein Atlas): Vesicles
Gene Ontology:
Biological process: myelination
Cellular component: cytoplasm; extracellular exosome
Genetic constraint (gnomAD): Loss-of-function variants: 43 observed, 64.82 expected, observed/expected ratio (o/e) 0.66, 90% interval 0.52 to 0.86. The upper end of that interval is the gene's LOEUF score, 0.86, which puts it in group 3 of 6, group 1 being the genes least tolerant of losing a copy. Missense variants: 777 observed, 787.06 expected, observed/expected ratio (o/e) 0.99, 90% interval 0.93 to 1.05. Synonymous variants: 289 observed, 299.38 expected, observed/expected ratio (o/e) 0.97, 90% interval 0.88 to 1.06.
Homologues: Orthologues: chimpanzee BCAS1 (99% identical), macaque BCAS1 (95% identical), dog BCAS1 (75% identical), rabbit BCAS1 (74% identical), rat Bcas1 (66% identical), guinea pig BCAS1 (66% identical), pig BCAS1 (65% identical), mouse Bcas1 (63% identical), tropical clawed frog bcas1 (31% identical).
Diseases named in the same sentence as BCAS1 in open-access papers:
BCAS1 is named in the same sentence as 29 diseases in open-access papers, as found by Europe PMC text mining. Sharing a sentence is not in itself a finding about the gene and the disease. The quoted sentences say what the papers report.
breast carcinoma (11 papers, 2013 to 2024). "Among the candidates that can also mediate the growth inhibitory action of the compound, we have further characterized the JQ1-associated downregulation of two important breast cancer oncogenes, BCAS1 and PDZK1." (PMID 28881673, 2017). "PDZK1 promotes estrogen-mediated growth of breast cancer cells, whereas BCAS1 undergoes gene amplification-associated overexpression in breast cancer and has been implicated in breast cancer progression." (PMID 28881673, 2017). "Since the BCAS1 gene was originally found in human breast carcinoma cells, its previous name was “breast carcinoma amplified sequence 1”." (PMID 35620461, 2022). "Lastly, in e-CSCs, BCAS1 (Breast carcinoma-amplified sequence-1) protein expression was up-regulated, by nearly 120-fold." (PMID 30760648, 2019). "In the last years, brain enriched myelin associated protein 1 (BCAS1), also known as breast carcinoma amplified sequence 1 or novel amplified in breast cancer 1, is a protein that has been stablished as a marker of early myelinating oligodendrocytes in the mouse and human brain." (PMID 38275289, 2024). "BCAS1 has been found to be highly expressed in breast cancer cell lines." (PMID 37559353, 2023). "Finally, in e-CSCs, BCAS1 (Breast carcinoma-amplified sequence-1) protein expression was up-regulated by >100-fold." (PMID 30760648, 2019). "Interestingly, expression microarray analyses indicate that, upon JQ1 administration, the antitumoral phenotype also involves downregulation of relevant breast cancer oncogenes such as the Breast Carcinoma-Amplified Sequence 1 (BCAS1) and the PDZ Domain-Containing 1 (PDZK1)." (PMID 28881673, 2017). "The association between IGFBP3 with epidermal growth factor receptor (EGFR), another breast cancer-related gene, may contribute to tumorigenesis in a manner similar to the long-range interactions between IGFBP3 and breast carcinoma amplified sequence (BCAS1-4) in MCF7 cells." (PMID 29149895, 2017).
multiple sclerosis (5 papers, 2020 to 2023). A progressive autoimmune disorder affecting the central nervous system resulting in demyelination. "Bcas1 expression defines a population of early myelinating oligodendrocytes in multiple sclerosis lesions and Bcas1-positive immature oligodendrocytes seem to be affected by α-synuclein–induced pathology in multiple system atrophy." (PMID 36436561, 2022). "In addition, BCAS1 is characteristically expressed in immature oligodendrocytes undergoing myelination, and BCAS1 expression identify cells involved in multiple system atrophy and multiple sclerosis." (PMID 36010884, 2022). "In addition, BCAS1(+) cells are known to be increased within the remyelinating areas of multiple sclerosis, suggesting that a portion of the BCAS1(+) cell population is engaged in the active regeneration of OLGs." (PMID 32727582, 2020).
glioblastoma (4 papers, 2022 to 2024). The most malignant astrocytic tumor (WHO grade IV). "Three proteins have been identified as upregulated in recurrent glioblastoma and highly heterogeneous across patients: brain enriched myelin associated protein 1 (BCAS1), inverted formin 2 (INF2), and F-Box Protein 2 (FBXO2)." (PMID 39513861, 2024). "Finally, a novel splice variant of BCAS1 has been linked with high proliferation and migration rate of the glioblastoma." (PMID 38275289, 2024). "This study analyzes the expression of BCAS1 in different tumor samples from patients with diffuse gliomas (17 oligodendrogliomas; 8 astrocytomas; 60 glioblastomas) and uncovers the molecular and ultrastructural features of BCAS1+ cells by immunostaining and electron microscopy." (PMID 38275289, 2024). "FBXO2-positive glioma cells were mostly associated with regions of the tumor with high immune reactivity and neurodevelopmental reactivation of the transcription program, while BCAS1 and INF2 were less specific and more widely diffused across the different regions of the glioblastoma." (PMID 39513861, 2024). "However, no specific mutation or modification occurred in the BCAS1 gene sequence according to the analysis results of The Cancer Genome Atlas Glioblastoma Multiforme (TCGA-GBM) data." (PMID 36010884, 2022).
glioma (4 papers, 2008 to 2024). A benign or malignant brain and spinal cord tumor that arises from glial cells (astrocytes, oligodendrocytes, ependymal cells). "Brain enriched myelin associated protein 1 (BCAS1) is a novel marker of immature oligodendrocytes and was proposed to contribute to tumorigenesis in non-central nervous system tumors." (PMID 38275289, 2024). "This, together with the co-expression of EGFR marker, associated with high malignancy gliomas, supports the possible tumorigenic capacity that the BCAS1+ population could display." (PMID 38275289, 2024). "In this case report, a compact cluster of BCAS1+ cells was described for the first time in a glioma." (PMID 38275289, 2024). "The capacity of the BCAS1+ cells to form nodules and its location close to the blood vessels in GB evokes a mechanism to glioma progression." (PMID 38275289, 2024). "In total, we confirmed 14 genes with glioma-specific splicing; seven were novel events identified by the exon expression array (A2BP1, BCAS1, CACNA1G, CLTA, KCNC2, SNCB, and TPD52L2)." (PMID 18474104, 2008).
Stroke (4 papers, 2020 to 2024). Sudden impairment of blood flow to a part of the brain due to occlusion or rupture of an artery to the brain. "In line with previous studies, we found increased Bcas1 levels after stroke which are likely to represent a compensatory mechanism of oligodendrocyte proliferation after hypoxia and energy deficiency." (PMID 32182846, 2020). "In this study, authors concluded that remyelination dysfunction could be attributed to insufficient maturation of BCAS1+ oligodendrocytes in stroke." (PMID 39877374, 2024). "That is to say, PE promotes remyelination after stroke via enhanced oligodendrocyte differentiation, as BCAS1 expression could identify newly generated oligodendrocytes." (PMID 36829205, 2023). "Both the number of BCAS1+ oligodendrocytes and Olig2+ oligodendrocytes were significantly elevated in PE rats, compared to MCAO and anti-activin-A rats, suggesting that microglia-associated activin-A in moderate PE stroke-rats promoted OPCs differentiation and oligodendrogenesis." (PMID 36829205, 2023). "To explore this possibility, we looked for apoptotic oligo lineage cells using TUNEL in combination with BCAS1 and PLP1 HCR across all time points after stroke (48 h, 5 d, 15 d, 30 d, 8 wk)." (PMID 37821228, 2023). "Previously, it was found that patients with stroke showed an increase in number of early-stage BCAS1+ oligodendrocytes, but not in late-stage BCAS1+ oligodendrocytes, compared to control donors without CNS pathology." (PMID 39877374, 2024).
multiple system atrophy (3 papers, 2020 to 2022). Multiple system atrophy (MSA) is a neurodegenerative disorder characterized by autonomic failure (cardiovascular and/or urinary), parkinsonism, cerebellar impairment and corticospinal signs with a median survival of 6-9 years. "However, a recent study reported that BCAS1 participates in oligodendritic cell neuromyelination and α-synuclein-induced pathology of multiple system atrophy (MSA)." (PMID 36010884, 2022).
prostate carcinoma (3 papers, 2013 to 2022). A carcinoma that arises from epithelial cells of the prostate gland. "Although BCAS1 was highly expressed in a variety of normal tissues including the prostate, it was lowly expressed in many different cancer types except prostate cancer." (PMID 35620461, 2022). "More importantly, BCAS1 can be used as an accurate marker in the urine cell-free DNA analysis for early prostate cancer diagnosis." (PMID 35620461, 2022).
schizophrenia (3 papers, 2021 to 2025). A major psychotic disorder characterized by abnormalities in the perception or expression of reality. "The absence of BCAS1 in knockout mouse models induced a schizophrenia-like behaviour suggesting an important role for normal myelination and brain function." (PMID 40042641, 2025).
bladder cancer (2 papers, 2013 to 2021). "We also analyzed the diagnostic accuracy of DNA integrity of three oncogenes (c-MYC, HER2, and BCAS1) which are known to be involved in the development of bladder cancer." (PMID 23509700, 2013).
brain tumors (1 paper, 2024). "A thorough comprehension of the role of BCAS1 not only in diffuse gliomas but also in other type of brain tumors would help to unravel its significance in tumor initiation, progression, and invasion." (PMID 38275289, 2024).
Calcium nephrolithiasis (1 paper, 2022). The presence of calcium-containing calculi (stones) in the kidneys. "Moreover, four SNPs at four loci, rs6667242 at ALPL (p = 0.02999, OR = 0.8331), rs1544935 at KCNK5 (p = 0.01341, OR = 0.7804), rs7328064 at DGKH (p = 0.007452, OR = 1.211) and rs13041834 at BCAS1 (p = 0.03897, OR = 0.8409), were suggestively associated with the risk of calcium nephrolithiasis." (PMID 35741705, 2022). "Moreover, four SNPs at four loci, rs6667242 at ALPL (p = 0.02999, OR = 0.8331), rs1544935 at KCNK5 (p = 0.01341, OR = 0.7804), rs7328064 at DGKH (p = 0.007452, OR = 1.211) and rs13041834 at BCAS1 (p = 0.03897, OR = 0.8409), were suggestively associated with calcium nephrolithiasis." (PMID 35741705, 2022).
Cognitive impairment (1 paper, 2020). Abnormal cognition is characterized by deficits in thinking, reasoning, or remembering. "Bcas1 levels were increased in AGAT-/- mice and correlate with cognitive impairment." (PMID 32182846, 2020).
diffuse Lewy body disease (1 paper, 2020). "The numbers of BCAS1-expressing oligodendrocytes that displayed a matured morphology negatively correlated with the density of pathological inclusions in MSA brains but not with that in Parkinson’s disease and diffuse Lewy body disease." (PMID 32727582, 2020).
ischemic stroke (1 paper, 2020). A stroke disorder caused by obstruction of blood flow to the brain, due to thrombotic (local blood clot formation) or embolic (due to a blood clot or other material traveling from another site) event. "The analysis revealed a significant upregulation of Bcas1 and Slc6a8 after ischemic stroke." (PMID 32182846, 2020).
oligodendroglioma (1 paper, 2024). A well-differentiated (WHO grade II), diffusely infiltrating neuroglial tumor, typically located in the cerebral hemispheres. "The observed proliferative capacity and distribution of BCAS1+ stellate cells, particularly in oligodendrogliomas, highlight BCAS1 as an interesting marker, warranting further investigation into its role in tumor malignancy." (PMID 38275289, 2024).
tumor (12 papers, 2012 to 2024). "BCAS1 (20q13.2), breast carcinoma amplified sequence 1, is amplified in a variety of tumor types and is associated with more aggressive tumor phenotypes." (PMID 22539939, 2012). "The capacity of the stellate BCAS1+ cells of clustering in nodules in OG, together with the increased number of BCAS1+ nodules found in more malignant OG, leads to the question of: what is the function of these clusters within the tumor?" (PMID 38275289, 2024). "In contrast to tumor BCAS1+ cells, non-tumor BCAS1+ cells exhibited a thinner layer of cytoplasm surrounding a smaller round nucleus and numerous highly branched processes." (PMID 38275289, 2024). "Intriguingly, when we evaluated the density of BCAS1+ cells in OG (quantification of the total number of BCAS1+ cells in tumor hot spots), our results depicted that grade 3 OG show a higher number of BCAS1+ nodules than grade 2 OG." (PMID 38275289, 2024). "In this study, we have identified a BCAS1+ cell population with proliferative capacity, suggesting its potential to be used as a biomarker for tumor malignancy." (PMID 38275289, 2024). "To examine the expression of BCAS1 in a representative cohort of diffuse gliomas, we collected samples from the tumor core of three diffuse glioma subtypes (i.e., 17 OG, 8 AS and 60 GB from different patients)." (PMID 38275289, 2024). "Our study provides the first evidence of BCAS1 expression in diffuse gliomas, with a heterogeneous pattern of distribution across all tumor subtypes." (PMID 38275289, 2024). "The majority of rearrangements were KIAA1549-BRAF rearrangements (n = 47; 85%), with only one tumor each harboring BCAS1, CCDC6, GIT2, or PTPRZ11 as a fusion partner." (PMID 36854806, 2023). "For cancer patients, the expression level of BCAS1 affects prognosis variously among different tumor types." (PMID 35620461, 2022). "BCAS1 resides in a region at 20q13 that is amplified in a variety of tumor types, and is reportedly required for myelination." (PMID 34646294, 2021). "Stellate and spherical BCAS1+ cells were detected in the three tumor subtypes analyzed." (PMID 38275289, 2024). "However, we found that tumor BCAS1+ cells express other oligodendroglial markers (i.e., OLIG2 and SOX10) related to immature stages within the oligodendrocyte linage." (PMID 38275289, 2024). "These cellular traits lead us to question if BCAS1-expressing cells could play a role in tumor aggressiveness, particularly in OG." (PMID 38275289, 2024). "This indicates that genes like BCAS1 are differentially expressed in tumours that contain the GATA3-ext mutation but not in tumours harbouring the GATA3-trunc mutation." (PMID 27588951, 2016). "Although the BCAS1 gene is often activated in cancer, a clear understanding of the role of BCAS1-SV1 in the tumor biology of GBM has remained elusive." (PMID 36010884, 2022). "In contrast, tumor BCAS1-expressing cells do not show a specific localization, do not contact myelin and their location can be dispersed throughout the tumor, forming small groups, or forming large clusters in the case of grade 3 OG." (PMID 38275289, 2024). "Our findings not only confirm the role of the BCAS1 gene in GBM tumor biology (although not the wild-type BCAS1 protein) but also serve as a molecular marker for the classification of GBM malignancy in the future." (PMID 36010884, 2022). "In addition, unlike oligodendrocytes, which have a classical condensed chromatin contacting the inner nuclear membrane, spherical BCAS1+ cells in the tumor exhibit loose chromatin that does not contact the nuclear membrane." (PMID 38275289, 2024). "Therefore, we confirmed that BCAS-SV1 but not BCAS1 can promote GBM tumor proliferation and migration." (PMID 36010884, 2022).
cancer (11 papers, 2012 to 2025). A tumor composed of atypical neoplastic, often pleomorphic cells that invade other tissues. "Brain-enriched myelin-associated protein 1 (BCAS1) is frequently highly expressed in human cancer, but its detailed function is unclear." (PMID 36010884, 2022). "Even BCAS1 is associated with drug resistance in cancer patients during treatment." (PMID 35620461, 2022). "Another group of differentially expressed proteins are associated with increased cancer cell motility and invasiveness, which include EphA2, BCAS1, S100 protein family members, Rho family members, Ral-A, Rab family members, Cdc42, MARCKS, Ezrin, Galectins 1 and 3 among others." (PMID 22417809, 2012). "METTL7A has protein interactions with cancer-related genes BCAS1 and GLIPR1L2, as well as post-transcriptional regulatory genes METTL8 and DDX55." (PMID 37547717, 2023). "Although the function of BCAS1 has yet to be described in detail, its expression is amplified in various human cancers, including breast and prostate cancer, leading to more aggressive tumors." (PMID 36010884, 2022). "Breast carcinoma-amplified sequence 1 (BCAS1) has recently been characterized as a marker protein for a pre-myelinating and myelinating oligodendrocyte subpopulation derived from NG2-positive OPCs." (PMID 33357244, 2020). "Importantly, the upregulated expression of CREB3L1 and BCAS1 and downregulated expression of ID1 and ID3 appeared least impacted by the co-existing 2nd (cancer) pathway variants based on visualisation of the heat maps." (PMID 40348815, 2025). "Studies have shown that the BCAS1 gene is greatly amplified on the chromosomes of some cancer patients, but whether and how BCAS1 is involved in the development of cancer are unclear." (PMID 36010884, 2022).
adenocarcinoma (1 paper, 2012). A common cancer characterized by the presence of malignant glandular cells. "Up-regulated expression of BCAS1 is significantly correlated with the high level amplification of 20q13 in adenocarcinomas of the gastro-esophageal junction." (PMID 22539939, 2012).
BCAS1 also shares sentences with these, for which no sentence is quoted: autism (3 papers); gastric cancer (3); astrocytomas (1); breast tumors (1); central nervous system tumors (1); cortical dysplasia (1); epilepsy (1); ovarian carcinoma (1); Parkinson disease (1); psoriasis (1); spina bifida (1).